AQP5 (aquaporin 5)
Diseases named in the same sentence as AQP5 in open-access papers (continued):
Sharing a sentence is not in itself a finding about the gene and the disease.
Obesity (1 paper, 2025). Accumulation of substantial excess body fat. "At the FAIM2 locus on chr 12q13.12, we observed known genes associated with obesity, eating patterns, and diabetes-related traits, including ASIC1, AQP2, AQP5, AQP6, RACGAP1, and AC025154.2 (AQP5-AS1) along with FAIM2." (PMID 39813287, 2025).
Palmoplantar hyperkeratosis (1 paper, 2023). Abnormal thickening of the skin localized to the palm of the hand and the sole of the foot. "While it remains unclear how defective epidermal-water-barrier function associated with mutant AQP5 leads to palmoplantar hyperkeratosis, the gain of function of mutated AQP5 may accelerate keratinocyte water uptake and explain the swelling of the epidermal stratum corneum after water exposure." (PMID 36768212, 2023).
polyp (1 paper, 2023). A usually exophytic mass attached to the underlying tissue by a broad base or a thin stalk. "In polyp samples from patients treated with fluticasone propionate in the 7 days before sinus surgery, there was a decrease in the expression of aquaporin-2 and aquaporin-5 compared to the control group." (PMID 37109177, 2023).
retinal ischemia (1 paper, 2023). A ischemic disease that involves the retina. "Interestingly, experimental retinal ischemia results in decreased retinal Aqp5 gene expression." (PMID 37958666, 2023).
salivary gland cancer (1 paper, 2021). A primary or metastatic malignant neoplasm that affects the major or minor salivary glands. "Also, we confirmed the expression of α-amylase and Aqp5 in AAV-ChAT transduced human salivary gland cancer cells (HSGs) (data not shown)." (PMID 33401680, 2021).
salivary gland diseases (1 paper, 2019). "In particular, the levels of anti-AQP5 IgG targeting A were even lower than non-SS SICCA, suggesting that anti-AQP5 IgG is associated with salivary gland diseases." (PMID 31684196, 2019).
sialolithiasis (1 paper, 2024). A concretion in the salivary gland. "AQP5 is critical for maintaining the normal physiology of the salivary glands, and its expression in salivary gland tissue could be affected by sialolithiasis and chronic salivary gland inflammation." (PMID 38380102, 2024).
steatosis (1 paper, 2025). Increased lipid within the cytoplasm of cells. "Our findings indicate that Aqp5 deficiency leads to a significant increase in lipid accumulation, suggesting distinct underlying mechanisms between pathological steatosis and lipid accumulation." (PMID 39947476, 2025).
thyroid tumor (1 paper, 2023). A benign or malignant neoplasm affecting the thyroid gland. "Our study provides evidence that OCLN, ZNF423, LYG1, and AQP5 mRNA markers can serve as reliable molecular markers for identifying NIFTP among other thyroid tumors." (PMID 37658903, 2023). "Our results suggest that OCLN, ZNF423, LYG1, and AQP5 mRNA markers might serve as reliable molecular markers for identifying NIFTP among other thyroid tumors, ultimately aiding in accurate diagnosis and management of NIFTP patients." (PMID 37658903, 2023).
uremia (1 paper, 2017). A clinical syndrome associated with the retention of renal waste products or uremic toxins in the blood. "The staining intensity of AQP5, UT-A1, and UT-B1 was different between uremia and normal renal function group." (PMID 29279852, 2017). "However, the expression of AQP5 in the sweat glands of the uremia is unclear, although the skin of the CKD patients was much drier than that of normal people." (PMID 29279852, 2017). "And there was no significant change in the localization of AQP5 in the skin of patients with uremia compared with healthy controls." (PMID 29279852, 2017). "However, in the uremia, the location and expression of AQP5 and UTs in skin have not been studied." (PMID 29279852, 2017).
vitreous hemorrhage (1 paper, 2020). Blood extravasation in the vitreous humor. "GCD and AQP5 genes expression levels were significantly lowered post-surgery in the sub-groups based on surgical intervention, non-suture; conjunctival non-opening and vitreous hemorrhage." (PMID 32437405, 2020).
tumor (80 papers, 2008 to 2026). "AQP5 involvement in tumor initiation and progression has been strongly linked with the activation of signaling pathways that can contribute to cancer cell migration, invasion and proliferation." (PMID 39941100, 2025). "AQP subtypes, such as AQP1, AQP3, and AQP5, have been implicated in various aspects of carcinogenesis, tumor progression, and invasion." (PMID 38057925, 2023). "Researchers have also demonstrated that co-expression of AQP3 and AQP5 is associated with aggressive tumor progression as well as poor outcomes in esophageal squamous cell carcinoma." (PMID 36672280, 2023). "In conclusion, our data suggested that the expression levels of AQP1, AQP3 and AQP5 were associated with regional lymph node metastasis, histological grading, and tumor location of CRC, respectively." (PMID 37334171, 2023). "Using TIMER and TISIDB, we found that the expression of AQP5 was associated with different tumor-infiltrating immune cells, especially macrophages." (PMID 35619903, 2022). "We found that AQP5 was significantly overexpressed in PAAD and that AQP5 expression was associated with tumor stage, tumor grade, and prognosis in patients with PAAD." (PMID 35619903, 2022). "For example, expression of transcripts encoding the tumor promoters Serpinb7, Aqp5, and Cd68 was induced by Src and suppressed by contact normalization." (PMID 35177067, 2022). "In fibroblasts, AQP5 overexpression induced tumor formation in nude mice, while AQP5-S156A mutation abolished tumor formation." (PMID 36212456, 2022). "Combined levels of AQP3 and AQP5 protein in biopsy samples from TNBC patients were positively associated with tumor size, lymph node metastasis, and likelihood of relapse, indicating increased aquaporin expression was linked to poorer survival." (PMID 33499000, 2021). "AQP5 expression has been associated with cellular migration, proliferation, and differentiation during neoplasia." (PMID 32075009, 2020). "In particular, it has been suggested that AQP5 involvement in intracellular signaling transduction pathways are implicated in tumor formation." (PMID 30893772, 2019). "A strong immunoreactivity for AQP3 and AQP5 is observed in the ductal cells of patients with pancreatic ductal adenocarcinomas that is associated to tumor aggressiveness and tumor differentiation, respectively." (PMID 29675407, 2018). "Using such an approach, we were unable to find significant differences in both AQP1 and AQP5 expression according to the underlying neoplasm." (PMID 24917931, 2014). "Data originating from several in vitro studies suggests that AQP5 is associated with increased proliferation, migration and decreased apoptosis in various tumor cell lines." (PMID 25344048, 2014). "We observed the coexpression of AQP3 and AQP5 to be associated with tumor stage, tumor grade, tumor metastasis, and patient prognosis." (PMID 24224160, 2013). "In this study, we also found that the overexpression of both AQP3 and AQP5 was associated with advanced tumor stage, positive distant metastasis, and unfavorable prognosis." (PMID 24224160, 2013). "Even after adjusting for histological grade and tumor stage, AQP5 overexpression in NSCLC was still significantly associated with earlier disease progression (p = 0.033; OR = 1.52; 95% CI: 1.04–2.23)." (PMID 18478076, 2008). "Therefore, the role of AQP1, AQP3 and AQP5 in tumor development is closely associated with their peroxiporin function." (PMID 39941100, 2025). "Elevated expression levels were linked with TNM stage (the categorization of cancerous tumours), distant metastasis and lymph node metastasis suggesting that AQP5 level of expression could be employed as a predictive biomarker." (PMID 38336645, 2024). "Interestingly, comparing with early stages, in later stages of PDAC, an aggressive tumor that frequently form metastasis in liver, AQP5 expression is almost undetectable, corroborating our findings and underlining the AQP5 contribution to tumor aggressiveness." (PMID 35455986, 2022).
tumor (continued). "Moreover, AQP1 and AQP3 protein expression was highest in poorly differentiated tumors, whereas AQP5 is more expressed in moderately differentiated tumors, suggesting that AQPs are associated with tumor aggressiveness." (PMID 33178018, 2020). "Furthermore, expression of AQP5 was found to be associated with cellular differentiation, lymph node invasion, and tumor staging." (PMID 24338153, 2014). "Association between AQP5 overexpression and the demographics of patients and tumor characteristics." (PMID 18478076, 2008). "AQP5 is linked to tumor invasiveness, although its prognostic impact remains unclear." (PMID 39596202, 2024). "AQP5 was found overexpressed in cancer cells and tumor tissues, strongly suggesting that it may be implicated in tumor formation by contributing to cell differentiation and migration through mechanisms involving AQP5 interplay with intracellular signaling transduction pathways." (PMID 27983600, 2016). "Immunohistochemical analysis of tumor sections demonstrated significant p-NF-κB upregulation in AQP5-overexpressing tumors compared to controls, accompanied by reduced apoptotic cells." (PMID 40760228, 2025). "Compared to existing biomarkers, such as CA19-9, which lacks specificity and sensitivity, AQP3 and AQP5 offer a mechanistic link to tumor biology, providing insights into disease progression and patient clinical outcomes." (PMID 40305202, 2025). "Among the AQPs, AQP1, AQP3 and AQP5 have been consistently identified as being aberrantly expressed in various tumor types." (PMID 39941100, 2025). "The results of tumor bearing experiment in nude mice (in vivo) showed that the tumor growth rate of AQP5 overexpression group was faster, and the tumor diameter and body weight of nude mice were significantly increased." (PMID 40760228, 2025). "This review focuses on the pivotal roles of aquaporins AQP1, AQP3 and AQP5 in tumor biology, emphasizing their significant contributions to cancer progression." (PMID 39941100, 2025). "After 5-FU treatment, the tumor volume became smaller, and the tumor volume in AQP5 overexpression group was significantly larger than that in control group." (PMID 40760228, 2025). "Compared to conventional biomarkers such as CA19-9, which lacks specificity and sensitivity, AQP3 and AQP5 provide a mechanistic link to tumor biology by modulating key oncogenic pathways." (PMID 40305202, 2025). "AQP3 expression levels are increased with cancer development from the early to late stages of the tumor, while AQP5 expression is augmented in the early stage but almost undetectable in later stages, showing its potential as a biomarker of this disease." (PMID 39941100, 2025). "By regulating tumour growth and apoptosis, AQP5 can play a significant role in carcinogenesis and tumour progression." (PMID 38336645, 2024). "Stimulating clues also derive from preliminary observations pointing to a beneficial effect of high AQP1 and AQP5 expression in subjects with biliary tract cancer, mainly in terms of longer survival, smaller tumor size, and depth of tumor invasion." (PMID 39596202, 2024). "Tumours that show elevated expression AQP5 also have a phosphorylated cAMP-protein kinase (PKA) consensus domain, which stimulates cellular proliferation." (PMID 38336645, 2024). "It has been shown that AQP5 induces tumour growth via stimulating the Ras-MAPK cascade, cyclin D1/CDK4 complexes, phosphorylating retinoblastoma protein in the nucleus, and culminating in the expression of cell proliferation-related genes." (PMID 38336645, 2024). "In the context of NSCLC, the overexpression of AQP1, AQP3, AQP4, and AQP5 has been demonstrated to facilitate tumor angiogenesis, as well as the proliferation, migration, and invasiveness of tumor cells." (PMID 39440058, 2024). "AQP5+ tumor-resident cells exhibit stem potential ex vivo, suggesting AQP5 as a biomarker for diagnosis, prognosis, and therapeutic targeting." (PMID 39335106, 2024).
tumor (continued). "In hepatocellular carcinoma, AQP5 promoted cell invasion and tumor metastasis in vitro and in vivo and induced EMT involving NFkB activation." (PMID 36768212, 2023). "On the basis of the articles analyzed in our paper, it can be concluded that the role of AQP5 in the process of neoplasm formation has been a subject of thorough research." (PMID 36766810, 2023). "The AQP1 expression, AQP3 expression and AQP5 expression were related to regional lymph node metastasis, histological grading, and tumor location of CRC, respectively." (PMID 37334171, 2023). "Knockdown of AQP5 significantly reduced the tumor formation rate of GC cells as well as the tumor weight and volume." (PMID 36372898, 2022). "The immunoblot analysis of tumor tissue was in concordance with the immunohistochemical findings of AQP5 expression." (PMID 36230831, 2022). "AQP5 and its upstream and downstream signaling pathways play a significant role in tumor proliferation, invasion, and metastases." (PMID 36114463, 2022). "Using the TISIDB database, we analyzed the correlation between AQP5 expression and 28 subtypes of tumor-infiltrating immune cells in different types of tumors." (PMID 35619903, 2022). "AQP3 and/or AQP5 silencing was related with weak cell–cell adhesion, suggesting an involvement of AQPs in tumor metastases." (PMID 35455986, 2022). "A second in vivo mouse model (Aqp5-IRES-creERT2 APK) study for comparative profiling of LGR5+ stem cell populations along the gastrointestinal tract confirmed the stem potential of tumor-initiating cells within the AQP5+ compartment." (PMID 35847914, 2022). "The relevance of AQP3 and AQP5 in cell migration and their implication in tumor progression was investigated in cells silenced for each paralog separately and simultaneously." (PMID 35455986, 2022). "The findings revealed that ANO1, AQP9, and BEST2 were upregulated in tumor tissues, and AQP5, SCN4A, and SCNN1G expression was upregulated in normal tissue from 12 HNSCC patients." (PMID 36389709, 2022). "We also found that the abundance of tumor-infiltrating immune cells was affected by different somatic copy number aberrations of AQP5 in PAAD." (PMID 35619903, 2022). "The expression of aquaporin-5 was restored in tumor-bearing mice injected with DMA before irradiation." (PMID 36230831, 2022). "Downregulation of AQP5 markedly suppresses cell growth and tumor growth in cultured GC-CSCs and xenograft mouse models." (PMID 36372898, 2022). "TIMER and TISIDB were used to analyze correlations among AQP5, tumor-infiltrating immune cells, and immunomodulators." (PMID 35619903, 2022). "We then used the TISIDB database to further explore the relationship between AQP5 levels and 28 tumor-infiltrating immune cell subtypes." (PMID 35619903, 2022). "The results showed that AQP5 knockdown significantly suppressed tumor growth, while AQP5 overexpression promoted tumor growth, as indicated by the xenograft tumor growth curve and tumor weight." (PMID 36372898, 2022). "In contrast, overexpression of AQP5 promoted the tumorigenicity of GC cells as well as the tumor weight and volume." (PMID 36372898, 2022). "Like the parental tumors, the outer layer of the solid pattern in PDOs was CK5+ p63+ basal cells, while the inner layer of tumor mass was CK8+ AQP5+ luminal cells." (PMID 36527158, 2022). "In TNBC, AQP5 overexpression correlated with tumor size, nodal status, local relapse/distant metastasis, and elevated Ki-67 expression." (PMID 36212456, 2022). "When treated with epigallocatechin gallate, the SKOV3 cell line showed reduced AQP5 expression while inhibiting the proliferation of tumor cells." (PMID 33271827, 2020). "Expression of AQP5 was evident in GCs and theca cells (TCs) in normal ovaries while immunohistochemistry revealed the presence of AQP5 in surface epithelium, fibroblast cells of the stroma and cells lining tumor and acini." (PMID 33271827, 2020).
tumor (continued). "In a mouse xenograft model, transplanted cells expressing wild type AQP5 markedly formed tumor nodule, whereas transplanted cells expressing S156A mutant did not." (PMID 32053992, 2020). "In the first case, the use of cisplatin reduced the expression of AQP5 and the rate of tumor cell proliferation." (PMID 33271827, 2020). "Besides its known expression in salivary and lacrimal glands, AQP5 was found to be overexpressed in cancer cells and tumor tissues, suggesting that it may be implicated in tumor formation, cell proliferation, migration and survival through multiple pathways that are not yet fully understood." (PMID 30893772, 2019). "Marker of alveolar type I cell lineage aquaporin 5 and heterogeneous expression of nuclear pERK were detected in the tumor." (PMID 29464089, 2018). "AQP5 mediates proliferation and migration of tumor cells through the EGFR/ERK/p38 MAPK signaling pathway." (PMID 28404978, 2017). "Together, these results suggest that high AQP5 expression promotes tumor cell proliferation, which agrees with the suppression of tumor cell proliferation observed here after AQP5 gene silencing." (PMID 28404978, 2017). "High AQP5 expression in colon, breast and pancreatic cancer cells affects the invasion, proliferation and metastasis of the tumor cells." (PMID 28404978, 2017). "AQP5 induced tumor proliferation by the activation of Ras-MAPK pathway, cyclin D1/CDK4 complexes, and then phosphorylated retinoblastoma protein in nucleus and caused transcription of genes related with cell proliferation." (PMID 25886458, 2015). "The cAMP-protein kinase (PKA) consensus site in AQP5 was preferentially phosphorylated and promoted cell proliferation ability in tumor." (PMID 25886458, 2015). "AQP5 has been suggested to act either as a tumor suppressor or as an oncogene, depending on the tumor type." (PMID 25217331, 2014). "Considering the potential role of AQP5 in tumor cell proliferation and migration, we examined the AQP5 mRNA and protein expression levels in the COVCAR cell lines." (PMID 25344048, 2014). "The growth rate of tumor size in mice receiving Lenti-AQP5-RNAi virus started to slow down after virus treatment." (PMID 25298246, 2014). "AQP5 overexpression was also observed more frequently in HCC tissues with high tumor grade than those with low grade (P = 0.009)." (PMID 24224160, 2013). "Cox's proportional hazard model revealed that AQP5 expression was an independent prognostic factor, and Chi-square analysis revealed that high AQP5 expression correlated to small tumor size in biliary tract carcinoma patients." (PMID 24224160, 2013). "Both AQP3 positive staining and AQP5 positive staining were localized in the cytoplasm and membrane of tumor cells in HCC tissues." (PMID 24224160, 2013). "Recent reports demonstrated that AQPs, particularly AQP1 and AQP5, are expressed in high grade tumor cells of a variety of tissue origins, and that AQPs are involved in cell migration and metastasis." (PMID 23468877, 2013). "AQP5 has been shown to be overexpressed in several types of cancers and contribute to tumor growth, progression and metastasis." (PMID 23148732, 2012). "Further efforts to identify promoter element responsible for the induced expression of AQP5 in several tumor cell lines suggested several potential cis-acting elements responsible for promoter activity." (PMID 18478076, 2008). "Our previous efforts to identify a promoter element responsible for the induced expression of AQP5 in several tumor cell lines suggested the existence of several potential cis-acting elements responsible for promoter activity." (PMID 18612408, 2008). "Moreover, in various cancers, AQPs such as AQP1, AQP3, and AQP5 exhibit correlated expression, reinforcing their significance in tumor progression." (PMID 40725460, 2025). "Thus, AQP3 and AQP5 are involved in tumor progression in HCC patients and are closely related to the prognosis of these patients." (PMID 39048663, 2024).